BRD4 (bromodomain containing 4)
Diseases named in the same sentence as BRD4 in open-access papers (continued):
Sharing a sentence is not in itself a finding about the gene and the disease.
schizophrenia (3 papers, 2017 to 2024). A major psychotic disorder characterized by abnormalities in the perception or expression of reality. "Single-nucleotide polymorphisms associated with schizophrenia, for example, link BRD4 to an increased susceptibility to this disorder." (PMID 36979729, 2023). "We highlight the possibility that SNPs lying within super-enhancers marked by BRD4 are more likely to be associated with an increased susceptibility to BC, PC, and schizophrenia." (PMID 28359301, 2017). "Notably, BRD4 pharmacological inhibition hampered the interaction between H2A.Z acetylation and BRD4, thus improving the transcriptional signature associated with schizophrenia in patient-derived neurons." (PMID 36979729, 2023). "As an H2A.Z acetylation reader, BRD4 mediates the onset and progression of schizophrenia, suggesting that targeting BRD4 or H2A.Z acetylation promises to be a potential treatment for schizophrenia." (PMID 39199381, 2024). "In a recent work, Farrelly and colleagues investigated histone acetylation in schizophrenia, identifying BRD4 as a possible target for treatment." (PMID 36979729, 2023).
steatosis (3 papers, 2020 to 2025). Increased lipid within the cytoplasm of cells. "(c) SAA achieves its hepatoprotective activity through inhibiting the BRD4‐mediated inflammatory response and hepatic steatosis." (PMID 32596881, 2020).
acute graft versus host disease (2 papers, 2021 to 2024). A syndrome of immunologically mediated tissue damage that may occur following an allogeneic transplant, usually affecting the skin, liver, and GI tract. "This asserts that the anti-inflammatory effects of BRD4 inhibition are independent of STAT1, which is a target of the currently FDA approved Jak1/2 inhibitor, ruxolitinib, for steroid refractory acute GVHD." (PMID 34722316, 2021).
acute kidney injury (2 papers, 2024 to 2026). Sudden and sustained deterioration of the kidney function characterized by decreased glomerular filtration rate, increased serum creatinine or oliguria. "In conclusion, our findings identify BRD4 as a key regulator of overexpression of the ATF4 and XBP1 UPR genes after acute kidney injury induced by IRI." (PMID 38481808, 2024).
adenovirus infection (2 papers, 2018 to 2021). "Further studies are required to delineate the mechanisms by which BRD4 utilizes to regulate adenovirus infection and transgene expression." (PMID 30068949, 2018).
adrenocortical carcinoma (2 papers, 2022 to 2023). "However, the expression levels, gene regulatory networks, prognostic value, and target prediction of BRD2, BRD3, and BRD4 in adrenocortical carcinoma (ACC) have not been fully elucidated." (PMID 36793283, 2023).
allergic asthma (2 papers, 2020 to 2023). A asthma with a basis in a pathological type I hypersensitivity reaction. "In summary, different layers of evidence support a critical role of BRD4 in allergic asthma and airway remodeling." (PMID 37686037, 2023). "This study provides evidence that BRD4 is involved in allergic asthma by modulating the Th2-mediated inflammatory response, which warrants further investigation." (PMID 37686037, 2023).
alopecia (2 papers, 2014 to 2022). Hair loss usually from the scalp. "Preserving OX40 signaling and BRD4 functions is critical in hair follicle stem cell fitness, survival, and proliferation, which has implications in treatment of hair loss and alopecia." (PMID 36256455, 2022). "Conditional deletion of Brd4 in hair follicle stem cells inhibited their proliferation during hair growth cycles, which constitutes the underlying mechanisms of alopecia." (PMID 36256455, 2022). "Conditional deletion of Brd4 in OX40-expressing cells induces prominent alopecia and severe dermatitis." (PMID 36256455, 2022). "In the present study, we demonstrate that conditional deletion of Brd4 using the Ox40-Cre recombinase induces tissue-specific skin inflammation characterized by profound alopecia and dermatitis." (PMID 36256455, 2022). "Brd4-depleted mice display reversible epidermal hyperplasia, alopecia, and decreased cellular diversity and stem cell depletion in the small intestine." (PMID 25242322, 2014).
Anxiety (2 papers, 2021 to 2023). Intense feelings of nervousness, tension, or panic often arise in response to interpersonal stresses. "In animal models, defective BRD4 was associated with impaired synaptic plasticity and memory formation, likely linking this protein to PTSD-related amnesia, depression, and anxiety, while at the same time indicating that BRD4 inhibitors may be therapeutic for SRD." (PMID 34776871, 2021).
Arthritis (2 papers, 2020 to 2024). Inflammation of a joint. "The OARSI scores demonstrated that BRD4 inhibition effectively alleviated arthritis in the rats." (PMID 39349832, 2024).
cataract (2 papers, 2017). Partial or complete opacity of the crystalline lens of one or both eyes that decreases visual acuity and eventually results in blindness. "A previous study indicated that Brd4-deficient mice exhibit syndromic abnormalities, including cataracts, similar to the symptoms observed in patients in this study." (PMID 28076398, 2017). "In conclusion, BRD4 may be a novel causative gene for an autosomal dominant syndromic congenital cataract disease." (PMID 28076398, 2017). "This phenotype of the BRD4 heterozygous mouse mutant is highly similar to that of our patients, including the short stature, cataracts, and brain malformation." (PMID 28076398, 2017). "We focused on the effect of the inhibition of endogenous BRD4 expression owing to the lack of studies supporting a link between BRD4 and cataracts or related disorders." (PMID 28076398, 2017).
Cerebral ischemia (2 papers, 2020 to 2021). Restriction of arterial blood supply to the brain associated with insufficient oxygenation to support the metabolic requirements of the tissue. "So far, only a few relevant reports as we know that show the possible connection between BRD4 and pyroptosis, which mainly exists in cerebral ischemia-induced brain damage and the progress of renal cell carcinoma." (PMID 33679744, 2021). "As we described in the introduction part, BRD4 was only reported to affect pyroptosis in cerebral ischemia and renal cancer." (PMID 33679744, 2021).
cholestasis (2 papers, 2020 to 2021). Impairment of the bile flow caused by obstruction within the liver, or outside the liver in the bile duct system. "Although BRD4 promotes hepatic inflammation and fibrosis in cholestasis, paradoxically, BRD4 is required for the antiinflammatory, antifibrotic actions of OCA-activated FXR." (PMID 33290278, 2020). "Not surprisingly, BRD4 has emerged as a potential drug target for numerous diseases, including cancer and metabolic diseases, such as cholestasis and NASH." (PMID 33290278, 2020).
chondrosarcoma (2 papers, 2023). A malignant cartilaginous matrix-producing mesenchymal neoplasm arising from the bone and soft tissue. "Furthermore, BRD3, together with BRD4, was shown to regulate the expression of matrix metalloproteinases (MMP) under pro-inflammatory conditions in chondrosarcoma cells." (PMID 38137409, 2023).
clear cell carcinoma (2 papers, 2022 to 2023). "In addition, high BRD4 expression was significantly associated with serous carcinoma and clear cell carcinoma." (PMID 35902869, 2022).
Cognitive impairment (2 papers, 2024 to 2025). Abnormal cognition is characterized by deficits in thinking, reasoning, or remembering. "In vivo findings further confirmed that synaptic loss and neuronal death, both of which contribute to cognitive impairment, were alleviated by restoring FAM134A expression through BRD4 inhibition in ethanol-fed mice." (PMID 40959274, 2025). "The cognitive impairment observed is generally more severe than in patients with mutations in the SMC1A, SMC3, BRD4, and RAD21 genes." (PMID 38673696, 2024). "Collectively, these findings suggest that pharmacological inhibition of BRD4 may alleviate ethanol-induced synaptic deficits, neuronal apoptosis, and cognitive impairment." (PMID 40959274, 2025). "In conclusion, our study highlighted that ER-phagy reduced by BRD4-mediated FAM134A downregulation in neurons exposed to ethanol induces chronic ER stress, resulting in synaptic dysfunction, neuronal apoptosis and cognitive impairment." (PMID 40959274, 2025).
colorectal tumor (2 papers, 2015 to 2017). "Our data revealed high-frequency mutations in BRD4 or BRD3 or both in 79 % (23/29) of colorectal tumors, which is, therefore, a novel finding." (PMID 29296220, 2017).
Cornelia de Lange syndrome 6 (2 papers, 2025). "In human patients, heterozygous variants in BRD4 can cause Cornelia de Lange syndrome 6 (OMIM 620568) characterized by microcephaly and long philtrum, CP, distal limb defects, retarded growth, heart defects, and neurodevelopmental delay." (PMID 40525707, 2025).
Cornelia de Lange-like syndrome (2 papers, 2021 to 2022). "Recently, we identified a missense mutation in BRD4 associated with a Cornelia de Lange-like syndrome that reduces BRD4 binding to acetylated histones." (PMID 34035299, 2021). "Patients with pathogenic variants in BRD4 develop Cornelia de Lange-like syndrome." (PMID 35887114, 2022).
coronary artery disease (2 papers, 2019 to 2023). "Modulation of transcription factor activity by scaffold proteins, e.g., bromodomain protein 4 (BRD4), is implicated in coronary artery disease by altering the balance of proliferation and apoptosis of smooth muscle cells." (PMID 31013688, 2019).
embryonal tumor (2 papers, 2020 to 2024). "Recently, two cases of CNS embryonal tumors harboring a BRD4::LEUTX fusion were described." (PMID 38500181, 2024). "Embryonal tumors with multilayered rosettes (ETMRs) which otherwise lack rosettes, a medulloepithelioma component, and neurocytic/neuropil-rich areas could also resemble embryonal tumors with BRD4::LEUTX fusions, but they are generally negative for OLIG2 and positive for LIN28A." (PMID 38500181, 2024).
embryonic carcinoma (2 papers, 2016 to 2024). "FLIP assays using P19 embryonic carcinoma cells transfected with GFP-tagged BRD4 show that GFP-BRD4 fluorescence is lost more slowly in the presence of trichostatin A (TSA), which is a histone deacetylase inhibitor, suggesting the affinity of BRD4 for chromatin is increased by histone acetylation." (PMID 27827996, 2016).
endometrial tumors (2 papers, 2022 to 2025). "In this study we sought to determine the impact of BRD4 recurrent focal deletions on gene expression, with a particular focus on how BRD4 isoform-level expression is altered in BRD4-amplified ovarian, breast, and endometrial tumors." (PMID 40112818, 2025). "In the present study, western blot and IHC analyses of BRD4 protein expression in EC and normal endometrial tissues showed that BRD4 is overexpressed in endometrial tumors and that nuclear BRD4 expression levels are negatively correlated with overall patient survival time." (PMID 35902869, 2022).
essential hypertension (2 papers, 2020 to 2023). Hypertension that presents without an identifiable cause. "It has been reported that blood BRD4 in essential hypertension (EH) patients is higher than in the healthy control and was positively correlated to systolic and diastolic blood pressure of enrolled subjects including patients with EH and healthy controls." (PMID 37509171, 2023). "BRD4 inhibiter JQ-1 treatment significantly decreased blood pressure in SHR rats, without significant changes in food intake and body weight, suggesting a potential role for BRD4 in the development of hypertension." (PMID 37509171, 2023). "Treatment with BRD4 inhibitor JQ-1 ameliorates AngII-induced hypertension, medial hypertrophy, and inflammation in vivo in mice, further underscoring the promise of such epigenetic modifiers for the treatment of human hypertension." (PMID 37509171, 2023).
focal segmental glomerulosclerosis (2 papers, 2016 to 2024). A renal disorder characterized by sclerotic lesions in the glomeruli. "However, Brd4 was detected in both tubular cells and interstitial cells in the kidney of patients with focal segmental glomerulosclerosis (FSGS) and IgA nephropathy." (PMID 27732564, 2016).
gastrointestinal stromal tumor (2 papers, 2020). "In gastrointestinal stromal tumours (GISTs), the function of bromodomain‐containing 4 (BRD4) remains underexplored." (PMID 31957165, 2020). "BRD4 has been documented to activate NF-κB pathway in gastrointestinal stromal tumor." (PMID 32527308, 2020).
Hypertension (2 papers, 2020 to 2023). The presence of chronic increased pressure in the systemic arterial system. "Several lines of evidence indicate the potential association between BRD4 and systemic hypertension in human and animal models." (PMID 37509171, 2023). "Despite these findings, the studies on BRD4 in systemic hypertension are much fewer so far." (PMID 37509171, 2023).
inflammatory bowel disease (2 papers, 2020 to 2025). A spectrum of small and large bowel inflammatory diseases of unknown etiology. "In addition to FXR, BRD4 has also emerged as an exciting potential therapeutic target for chronic liver disease and inflammatory bowel disease, as well as cancer and neurological disorders." (PMID 33290278, 2020).
injury (2 papers, 2023 to 2025). Damage inflicted on the body as the direct or indirect result of an external force, with or without disruption of structural continuity. "Both studies provide a foundation for targeting BRD4 in the prevention and treatment of cadmium-induced kidney injury." (PMID 40278574, 2025).
Insulin resistance (2 papers, 2021 to 2022). Increased resistance towards insulin, that is, diminished effectiveness of insulin in reducing blood glucose levels. "Because HFD-induced obese mice develop glucose intolerance and insulin resistance, we next compared the insulin sensitivity of WT and Brd4-CKO mice fed a ND or a HFD by the glucose tolerance test (GTT) and insulin tolerance test (ITT)." (PMID 33830083, 2021). "Myeloid lineage-specific BRD4 knockout mice fed a high-fat diet display reduced local and systemic inflammation and improved insulin sensitivity, while overexpression of BRD2 in white adipose tissues from wild-type mice induces insulin resistance." (PMID 36015180, 2022). "Brd4 occupied the promoter and enhancers of Gdf3 to facilitate PPARγ-dependent expression of Gdf3, which in turn suppressed ATGL expression and lipolysis in adipocytes, resulting in the increased fat accumulation and insulin resistance." (PMID 33830083, 2021).
Intellectual disability (2 papers, 2022). "Heterozygous, multigenic deletions in chromosome 19, encompassing BRD4, have been linked to intellectual disability in multiple probands." (PMID 35615272, 2022). "Moreover, recent studies identified four patients with intragenic mutations in BRD4, resulting in a CdLS-like phenotype characterized by intellectual disability, microcephaly, developmental delay, and many of the CdLS facial features." (PMID 35615272, 2022).
intervertebral disc degeneration (2 papers, 2020 to 2021). "Studies have shown that inhibition of BRD4 can inhibit MAPK signal and reduce spinal cord ischemia reperfusion injury and inhibition of BRD4 can inhibit the expression of MAPK signaling pathway in diabetic intervertebral disc degeneration." (PMID 34674702, 2021).
kidney damage (2 papers, 2023). "In fact, several preclinical studies have shown that BDR4 regulates pro-inflammatory and pro-fibrotic genes.The iBETs JQ1 that specifically inhibits BRD4 has been previously demonstrated to inhibit proinflammatory gene transcription in renal cells and in experimental kidney damage." (PMID 37237996, 2023).
Lewis lung carcinoma (2 papers, 2024 to 2025). "Using a myeloid-specific BRD4-knockout mouse model (Brd4fl/fl LysM-Cre), myeloid lineage loss of BRD4 decreased splenic and tumor MDSCs in the Lewis lung carcinoma (LLC) model." (PMID 40762981, 2025).
liver disease (2 papers, 2021 to 2025). "In order to determine the biological role of BRD4 in alcohol-associated liver disease in clinical setting, BRD4 expression was compared assayed in liver biopsy samples between healthy controls and ALD patients by immunofluorescence." (PMID 34149421, 2021).
lung squamous cell carcinoma (2 papers, 2019 to 2020). "In lung squamous cell carcinoma, METTL3 interacts with eukaryotic translation initiation 3 h to accelerate tumorigenicity by promoting translation of oncogenic mRNAs, such as Bromodomain-containing protein 4 (BRD4)." (PMID 32513173, 2020).
myeloid leukemia (2 papers, 2019). A clonal proliferation of myeloid cells and their precursors in the bone marrow, peripheral blood, and spleen. "In order to characterize the role of BRD4 in the disease pathogenesis, a panel of myeloid leukemia cell lines was treated with JQ1, an inhibitor of both BRD4 isoforms and other BET protein members." (PMID 30761268, 2019).
myeloid malignancies (2 papers, 2022). "SMARCA4 also interacts with BRD4 to promote MYC-driven transcriptional programs in myeloid malignancies and BRD9 interacts with BRD4 to facilitate ncBAF recruitment to chromatin in embryonic stem cells." (PMID 35323214, 2022).
myeloproliferative neoplasm (2 papers, 2025). A clonal hematopoietic stem cell disorder, characterized by proliferation in the bone marrow of one or more of the myeloid (i.e., granulocytic, erythroid, megakaryocytic, and mast cell) lineages. "Similarly, in myeloproliferative neoplasms (MPNs) and lymphoma, BRD4 is implicated in the activation of inflammatory cytokine signaling and abnormal cell proliferation." (PMID 40374809, 2025). "Bromodomain (BET) inhibitors against BRD4, such as pelabresib, target both oncogenic JAK/STAT signaling and inflammatory NF-κB pathways in myeloproliferative neoplasms (MPNs)." (PMID 40140631, 2025).
Myocardial fibrosis (2 papers, 2021 to 2023). "Inhibition of BRD4 could block agonist-induced pathological hypertrophy in human induced pluripotent stem cell-derived cardiomyocytes, and attenuate TAC-induced myocardial fibrosis in mice." (PMID 34925046, 2021). "Inhibition of BRD4 attenuates TGF-β-induced endothelial-mesenchymal transition and cardiac fibrosis and BRD4 may act as a Keap1/Nrf2 upstream regulatory target to regulate oxidative stress and myocardial fibrosis." (PMID 37699016, 2023).
preeclampsia (2 papers, 2020 to 2025). Preeclampsia is a hypertensive disorder of pregnancy that is characterized by new-onset hypertension with proteinuria presenting after 20 weeks of gestation, and depending on mild or severe forms may initially present with severe headache, visual disturbances, and hyperreflexia. "Studies have shown that miR-101 plays a role in the formation of preeclampsia by reducing the expression of BRD4 protein, resulting in the inhibition of the NF-κB/CXCL11 signaling pathway and ultimately enhancing the proliferation and movement capabilities of placental trophoblast cells." (PMID 40104134, 2025).
progressive supranuclear palsy (2 papers, 2024). A rare late-onset neurodegenerative disease characterized by supranuclear gaze palsy, postural instability, progressive rigidity, and mild dementia. "Additionally, we identified a mutant form of Brd4 in Progressive supranuclear palsy patients, which attenuates the ability of Brd4 to promote cell competition by disrupting its interaction with the promoter of Spock2." (PMID 39010274, 2024).
prostate adenocarcinoma (2 papers, 2019 to 2025). "Our findings revealed a statistically significant positive correlation between BRD4 and ROR1, particularly in prostate adenocarcinoma and invasive breast carcinoma." (PMID 39816690, 2025). "BRD4 methylation levels at the cg17726535 locus were lower in cancer tissues than in normal tissues in BLCA, BRCA, COAD, KIRP, and prostate adenocarcinoma." (PMID 30988278, 2019).